EPO (erythropoietin)
Diseases named in the same sentence as EPO in open-access papers (continued):
Sharing a sentence is not in itself a finding about the gene and the disease.
Renal cyst (9 papers, 2014 to 2024). A fluid filled sac in the kidney. "One patient, with high erythropoietin levels and acquired multiple bilateral renal cysts, developed clinical hyper-viscosity symptoms, and was treated with serial phlebotomies." (PMID 32546701, 2020). "Erythropoietin (EPO), renin-angiotensin system, insulin-like growth factor, male gender and renal cysts are some of the factors that seem to play a role in post-renal transplant erythrocytosis." (PMID 32546701, 2020). "Most of the patients had multiple acquired renal cysts, which is a potential source of erythropoietin." (PMID 31266452, 2019). "Positive EPO staining of renal cysts in the resected polycystic kidney and sustained sEPO elevation following the nephrectomy allowed us to predict EPO production in the renal cysts of the contralateral polycystic kidney." (PMID 25295086, 2014). "This clinical course led us to consider EPO production in the contralateral polycystic kidney, as it was possible that not only RCC, but also renal cysts in ADPKD produce EPO." (PMID 25295086, 2014). "However, erythrocytosis can occur in patients with cystic diseases of the kidney and renal artery stenosis due to upregulation of hypoxia-inducible factors (HIFs) and increased EPO production." (PMID 34692308, 2021). "The extremely high EPO concentration in the cyst fluid supported the hypothesis of EPO production from the renal cysts in ADPKD." (PMID 25295086, 2014). "In addition, the renal cyst fluid exhibited an extremely high EPO concentration of 2,680 mU/ml in the surgically resected polycystic kidney, suggesting EPO production from the renal cysts." (PMID 25295086, 2014). "The high EPO levels in the cyst fluid further confirmed EPO production in the renal cysts." (PMID 25295086, 2014). "The sustained elevation of sEPO may have been due to EPO production from the renal cysts in the contralateral polycystic kidney." (PMID 25295086, 2014). "Positive EPO staining of the renal cysts in the resected polycystic kidney and sustained sEPO elevation following nephrectomy led to the hypothesis of EPO production in the renal cysts of the contralateral polycystic kidney." (PMID 25295086, 2014). "It is not clear whether renal cysts produce EPO or simply cause local ischemic injury by compressing adjacent renal tissue leading to local renal hypoxia and to increased EPO production." (PMID 32546701, 2020). "In addition, the sEPO and EPO levels in a renal cyst were determined by enzyme immunoassay." (PMID 25295086, 2014). "In addition, a high risk of RCC development has been reported for ACDK patients, indicating that EPO production in renal cysts may be involved in RCC development." (PMID 25295086, 2014). "Therefore, renal cysts occasionally produce EPO in patients undergoing chronic dialysis." (PMID 25295086, 2014). "In conclusion, the present study demonstrated EPO production in RCC arising from ADPKD and the renal cysts of ADPKD." (PMID 25295086, 2014). "Immunohistochemical analyses to detect EPO were performed on RCC and renal cysts." (PMID 25295086, 2014). "Therefore, in the current study, EPO production by RCC and renal cysts was analyzed in the surgically resected polycystic kidney, by immunohistochemistry and enzyme immunoassay (EIA)." (PMID 25295086, 2014). "EPO production was observed in RCC and the renal cysts in ADPKD." (PMID 25295086, 2014).
retinal ischemia (9 papers, 2014 to 2022). A ischemic disease that involves the retina. "Consistent with these notions, systemic applied recombinant EPO protected EPO-deficient mice against profound retinal ischemia damage in RGCs." (PMID 28289375, 2017). "Systemic administration of recombinant human EPO (rhEPO) before or immediately after retinal ischemia was found to not only reduce histopathological damage and promote functional recovery in electroretinography, but also decrease apoptotic neurons." (PMID 28289375, 2017). "The neuroprotective effect of EPO on oligemic/ischemic retinas was suggested to related to the down-modulation of glial reactivity usually observed in hypoxic conditions, such as normal-tension glaucoma and retinal ischemia." (PMID 36555679, 2022). "Therefore, glial reactivity may enhance neurodegeneration in hypoxic conditions, like normal-tension glaucoma and retinal ischemia, and erythropoietin is thus a candidate to be clinically applied after the detection of decreased retinal blood flow." (PMID 29694605, 2018). "Such alterations in the endothelial cells of the retinal vessels lead to retinal ischemia, which stimulates the production of angiogenic factors such as VEGF and erythropoietin (EPO)." (PMID 34322687, 2021). "On the other hand, high-altitude hypoxia triggers the release of erythropoietin (EPO), a general tissue-protective cytokine which was shown not only to protect neurons following retinal ischemia in vivo, but also to improve their recovery following injury." (PMID 25738162, 2014). "They injected a dose of 2000 IU which is 800 times the vitreous concentration of the upregulated EPO level in retinal ischemia, which is 20 folds the level in nonischemic situations." (PMID 30647957, 2018).
sarcopenia (9 papers, 2019 to 2025). Progressive decline in muscle mass due to aging which results in decreased functional capacity of muscles. "In the sarcopenia samples, pathways such as type 2 papillary renal cell carcinoma, EPO-NF-κb pathway, and RUNX3 regulates CDKN1A transcription were significantly enriched." (PMID 41463417, 2025). "Pharmaceutical interventions for treating acute sarcopenia have included growth hormone (GH), testosterone, and erythropoietin (EPO) injections." (PMID 39458423, 2024). "Study 7 tried to include EPO as a drug to treat sarcopenia when used as a perioperative red blood cell mobilization drug in patients with FNF." (PMID 32993140, 2020). "The authors found that EPO improved the muscle strength of female patients with sarcopenia during the perioperative period, increased muscle mass of both women and men to a certain degree and significantly reduced the incidence of complications during the preoperative period." (PMID 32993140, 2020). "Some researchers have discovered that erythropoietin can be a potential treatment option for female patients with FNF and sarcopenia because it improves perioperative muscle strength." (PMID 40168411, 2025). "Study 7 assessed the effects of recombinant human erythropoietin (EPO), already used in in sarcopenic patients for perioperative recovery, in patients with femoral intertrochanteric fracture and sarcopenia, to investigate its potential benefits on postoperative rehabilitation." (PMID 32993140, 2020). "In summary, EPO could improve the muscle strength of female patients with sarcopenia during the perioperative period-but not revert sarcopenia itself." (PMID 33809573, 2021).
Telangiectasia (9 papers, 2014 to 2025). Telangiectasias refer to small dilated blood vessels located near the surface of the skin or mucous membranes, measuring between 0.5 and 1 millimeter in diameter. "Erythropoietin has the effect of promoting angiogenesis, which may aggravate the condition of telangiectasias or intrapulmonary shunting, whereas hypoxia caused by intrapulmonary shunting may in return lead to a further elevation of erythropoietin." (PMID 35663307, 2022). "The rapid drop in her monoclonal component, hematocrit, and serum erythropoietin was followed by the total resolution of both her telangiectasias and leukocytoclastic vasculitis, confirming a dramatic response to plasma cell‐directed therapy." (PMID 36467823, 2022). "The increase of serum erythropoietin or the M-protein, as well as the reemergence of telangiectasias, may be used as markers of relapse." (PMID 36358666, 2022).
Ureteral obstruction (9 papers, 2013 to 2024). Obstruction of the flow of urine through the ureter. "In this study, EPO expression was reduced after unilateral ureteral obstruction in control animals, but in Sult1a1-KO mice, EPO mRNA expression improved considerably, associated with a reduction in IS levels, as well as kidney fibrosis and inflammation." (PMID 39591250, 2024). "Moreover, the therapeutic effect of EPO was evaluated in murine unilateral ureteral obstruction (UUO) model." (PMID 34059008, 2021). "In a model of tubulointerstitial fibrosis induced by unilateral ureteral obstruction in mice, increased collagen I protein content and an almost complete disappearance of erythropoietin mRNA expression were observed in the ureteral ligated kidney with respect to the contralateral control." (PMID 28857467, 2018). "Indeed, MSC-EVs incubated with EPO showed a greater benefit in unilateral ureteral obstruction in vivo and in vitro." (PMID 28638822, 2017). "Interestingly, erythropoietin (EPO) showed to protect renal tubular basement membrane through EVs in a mouse model of renal tubule-interstitial fibrosis induced by unilateral ureteral obstruction." (PMID 28638822, 2017). "Here, we evaluated the inhibitory effects of microparticles (MPs) derived from human EPO gene-transfected kidney mesenchymal stem cells (hEPO-KMSCs) against TGF-β1-induced EMT in Madin-Darby canine kidney (MDCK) cells and against TIF in mouse kidneys with unilateral ureteral obstruction (UUO)." (PMID 32993806, 2020).
AIDS (8 papers, 2012 to 2025). A syndrome resulting from the acquired deficiency of cellular immunity caused by the human immunodeficiency virus (HIV). "The suggestion is that use of EPO will help a great deal in minimizing the risk of HIV/AIDS via blood transfusion when not screened properly." (PMID 23978045, 2013).
Anxiety (8 papers, 2008 to 2025). Intense feelings of nervousness, tension, or panic often arise in response to interpersonal stresses. "Chronic dosing of the BBB-penetrating cTfRMAb-EPO fusion protein reversed altered anxiety and hyperactive phenotypes and reduced phosphorylated tau and microgliosis, demonstrating therapeutic effects in a PS19 transgenic mouse model of tauopathy." (PMID 37111315, 2023). "Yet, there has been little data concerning the potential influence of EPO on behavioural indices of anxiety." (PMID 24019878, 2013). "In addition, EPO did reverse the stressor-induced reduction of open field exploration and suppression of entries into the open arm of an elevated plus maze, suggesting that EPO can counteract anxiety-like effects induced by the stressor exposure." (PMID 24019878, 2013). "Our data showed that EPO can increase hippocampal neurogenesis and promote anti-depressant and anti-anxiety-like effects, and that mTOR might be an important mediator in at least some of these outcomes." (PMID 24019878, 2013). "As the center of the arena is particularly apt in eliciting anxiety-related avoidance, it might be the case that the anxiolytic effects of EPO were limited." (PMID 24019878, 2013). "Although the present investigation suggests that EPO could have beneficial anti-depressant or anti-anxiety like effects in the face of stressors, this cytokine might have clinically important effects for a range of other conditions in which neuroplasticity is disturbed." (PMID 24019878, 2013). "Hence, the present study assessed the impact of EPO upon a range of depressive- and anxiety-like behaviours elicited by a social defeat stressor in mice, and whether EPO would augment hippocampal neurogenesis." (PMID 24019878, 2013). "Chronic dosing of cTfRMAb-EPO both reduced locomotion hyperactivity and altered anxiety-like behavior in the PS19 mice, which suggests that administering the BBB-penetrating EPO analog had a positive effect in this mouse model of tauopathy." (PMID 37111315, 2023). "A small number of studies have shown a weak correlation between elevated plus behavior and social behavior in BALB mice, and none of the previous studies on the effects of EPO and its derivatives in social behavior also examined anxiety-related behavior." (PMID 40137869, 2025). "There was no EPO effect on anxiety, spontaneous activity, exploratory behavior, and motor performance (all P > 0.05)." (PMID 18782446, 2008). "Moreover, anxiety levels were increased in IH as compared to normoxia, while no changes in anxiety emerged in EPO-treated mice." (PMID 22759774, 2012). "Treatment with EPO + MLT, but not EPO alone, normalized total time spent in the peripheral (p = 0.024) and neutral zones (p = 0.038), consistent with typical rat behavior, appropriate anxiety and general avoidance of open areas." (PMID 29706928, 2018).
aplastic anemia (8 papers, 2005 to 2026). Anemia resulting from bone marrow failure (aplastic or hypoplastic bone marrow). "Previous research has indicated that P. copri can alleviate liver fibrosis and regulate immunity in patients with severe aplastic anemia, and its homologous species, Prevotella 9, is positively correlated with EPO levels." (PMID 40525868, 2025). "In 1977, Miyake and his colleges isolated native human erythropoietin (EPO) from urine of patients with aplastic anemia." (PMID 26557695, 2015). "The main concern has been the development of anti-EPO neutralizing antibodies and consequently, aplastic anemia." (PMID 15910687, 2005). "Moreover, it took intensive research work over the past 50 years to identify EPO as the major driver of BM erythropoiesis, purify it from urine derived from patients with aplastic anemia by Goldweisser’s group, clone the EPO gene and produce recombinant EPO." (PMID 34440909, 2021).
bone marrow failure (8 papers, 2009 to 2023). "Traditionally, treatment options for bone marrow failure in patients with DC include anabolic steroids (for example, oxymetholone), granulocyte macrophage colony-stimulating factor, granulocyte colony-stimulating factor and erythropoietin." (PMID 19830116, 2009).
cardiac arrest (8 papers, 2010 to 2023). Cessation of breathing and/or cardiac function. "In a small study evaluating the effects of erythropoietin in cardiac arrest patients, the CPC 1 rate was higher in the treated group (55% vs. 38%); however, these results were not confirmed in a larger randomized study." (PMID 36291308, 2022). "The aim of the present study was to investigate the effect of EPO administration on renal function in an established model of cardiac arrest and resuscitation." (PMID 27847811, 2016). "In HS-65BV+VP, EPO attenuated increases in lactic acid, consistent with a beneficial effect at the mitochondrial level as we have reported in a rat model of cardiac arrest." (PMID 25365317, 2014). "We have reported beneficial effects of EPO for resuscitation from cardiac arrest in animal models and in human victims of sudden cardiac arrest." (PMID 25365317, 2014). "We believe our data have important clinical implications, and propose that EPO treatment may be beneficial for the retention of cognitive functions of the cardiac arrest patient." (PMID 23497299, 2013). "Our results confirm those of Popp and colleagues showing lack of neuroprotective efficacy of EPO in a rat model of cardiac arrest imposing a 8 minutes ischemic insult to the brain." (PMID 23497299, 2013). "The hypothermia/EPO combination is used in out-of-hospital cardiac arrest and this combination can improve the survival rate in adults, but to date there are no data on combined EPO/hypothermia treatment in neonatal HI." (PMID 21629441, 2010).
chronic obstructive pulmonary disease (8 papers, 2017 to 2024). A chronic and progressive lung disorder characterized by the loss of elasticity of the bronchial tree and the air sacs, destruction of the air sacs wall, thickening of the bronchial wall, and mucous accumulation in the bronchial tree. "In the remaining 6 cases, the hematological abnormality was finally classified as secondary erythrocytosis (patients E9-E14) due to kidney cancer with increased endogenous EPO levels (patient E9) and chronic obstructive pulmonary disease (COPD, 5 patients: E10-E14)." (PMID 28422729, 2017). "Diurnal variation of serum EPO levels can be detected in normal subjects: the nadir occurred at daytime, the peak concentration happened early in the morning, but this phenomenon could not be observed in chronic obstructive pulmonary disease." (PMID 28280920, 2017).
cognitive decline (8 papers, 2016 to 2022). "Given that the EPO receptor is widely expressed in the nervous system and that EPO easily crosses the intact blood–brain barrier, EPO supplementation is able to rescue cognitive decline in aged rats and restore impaired memory in vascular dementia (VaD) rat models." (PMID 31484803, 2019).
colorectal cancer (8 papers, 2018 to 2026). A primary or metastatic malignant neoplasm that affects the colon or rectum. "EPOR knockdown is a key approach to investigate erythropoietin signalling in colorectal cancer development and its potential interaction with SOCS6." (PMID 41514679, 2026). "One option to limit the use of PRBC is to enhance hemoglobin levels perioperatively via the substitution of erythropoietin, although a study from 2009 which also included patients undergoing surgical resection of primary colorectal cancer could not derive a recommendation for such a procedure." (PMID 35354485, 2022).
familial erythrocytosis (8 papers, 2018 to 2023). "Primary polycythemia is caused due to mutations in erythropoietin (EPO) receptor or Janus Kinase 2 (JAK2)." (PMID 36811053, 2023). "A review of the literature on recently reported mutations in patients with non-MPN erythrocytosis, highlighted the role of some known genes associated with familial erythrocytosis, such as EPO, HBB, VHL EGLN1, EPAS1, and EPOR." (PMID 36290845, 2022). "Primary polycythemia occurs due to somatic and germline mutations in erythroid, granulocytic and megakaryocytic progenitors with hypersensitive erythropoietin receptors (EPOR), leading to their clonal myeloproliferation with plasma erythropoietin (EPO) level below or in the normal range." (PMID 29534684, 2018).
hemolysis (8 papers, 2019 to 2025). Disruption of the integrity of the erythrocyte membrane causing release of hemoglobin. "Well-known causes of low hemoglobin levels in SCA are chronic hemolysis, ineffective erythropoiesis, nutritional disturbances, and reduced erythropoietin production." (PMID 35855023, 2022). "Our findings indicate that marathon running induces hemolysis and hematuria and that the body compensates for this by producing erythropoietin and elevating MCHC and MCH in the recovery period." (PMID 31244673, 2019).
liver disease (8 papers, 2014 to 2024). "Liver disorders can impair hepatocellular function, leading to reduced synthesis and secretion of proteins involved in erythropoiesis, such as erythropoietin (EPO)." (PMID 37431329, 2023). "In contrast, a recent study in chronically HCV-infected patients has showed that liver disease activity has a negative impact on erythropoiesis with compensatory higher but blunted EPO responses." (PMID 29258550, 2017).